MIR542 (microRNA 542)
Synonyms: hsa-mir-542; MIRN542; mir-542
Gene: MicroRNA gene on chromosome X (134,541,341 to 134,541,437, reverse strand). Ensembl gene ENSG00000207784.
Gene Ontology:
Biological process: miRNA-mediated post-transcriptional gene silencing
Cellular component: RISC complex
Homologues: Orthologues: chimpanzee MIR542 (100% identical), macaque mml-mir-542 (97% identical), mouse Mir542 (84% identical), guinea pig MIR542 (80% identical), pig ssc-mir-542 (78% identical).